OR6C6 (olfactory receptor family 6 subfamily C member 6)
Description:
Odorant receptor.
Tractability: Antibody: its Gene Ontology location is reachable by antibodies, with high confidence; UniProt places it where antibodies can reach, with medium confidence; UniProt predicts a signal peptide or a membrane-spanning region.
Gene: Protein-coding gene on chromosome 12 (55,293,988 to 55,296,569, reverse strand). Ensembl gene ENSG00000188324.
Subcellular location: Cell membrane
Subcellular location (Human Protein Atlas): Lipid droplets; Plasma membrane
Pathways (Reactome):
Sensory Perception: Expression and translocation of olfactory receptors
Gene Ontology:
Molecular function: olfactory receptor activity; G protein-coupled receptor activity
Biological process: detection of chemical stimulus involved in sensory perception of smell; G protein-coupled receptor signaling pathway
Cellular component: plasma membrane; membrane
Genetic constraint (gnomAD): Missense variants: 339 observed, 305.82 expected, observed/expected ratio (o/e) 1.11, 90% interval 1.01 to 1.21. Synonymous variants: 117 observed, 113.84 expected, observed/expected ratio (o/e) 1.03, 90% interval 0.88 to 1.2.
Homologues: Orthologues: chimpanzee OR6C6 (99% identical), dog OR6C6 (90% identical), rabbit OR6C6 (89% identical), mouse Or6c6 (87% identical), rat Or6c6b (86% identical), dog OR6C6J (85% identical), mouse Or6c6c (85% identical), rat Or6c6i (85% identical), rat Olr951 (84% identical), dog OR6C6K (78% identical). Paralogues in human: OR6C70 (73% identical), OR6C74 (69% identical), OR6C76 (69% identical), OR6C75 (69% identical), OR6C65 (67% identical), OR6C2 (65% identical), OR6C3 (65% identical), OR2AP1 (63% identical), OR6C4 (62% identical), OR6C1 (62% identical), OR6C68 (60% identical), OR6T1 (44% identical), and 6 more.
Diseases named in the same sentence as OR6C6 in open-access papers:
OR6C6 is named in the same sentence as 1 disease in open-access papers, as found by Europe PMC text mining. Sharing a sentence is not in itself a finding about the gene and the disease.
OR6C6 shares sentences with these, for which no sentence is quoted: preeclampsia (1 paper).